NF1 (neurofibromin 1)
Diseases named in the same sentence as NF1 in open-access papers (continued):
Sharing a sentence is not in itself a finding about the gene and the disease.
peripheral nerve tumors (16 papers, 2012 to 2025). "MES tumors are characterized by high NF1 expression, while PN tumors frequently exhibit PDGFRA mutations and contain tumor cells similar to oligodendrocyte progenitors and neural progenitors." (PMID 40331985, 2025). "A relevant contribution to data sharing and integration for peripheral nerve tumors associated with NF1 is represented by the recently updated Johns Hopkins NF1 Biorepository." (PMID 41463204, 2025). "Another methylation study on normal Schwann cells and NF1-associated PN tumor samples reported that a low level of methylation in NF1 gene promoters was found in PN tumors." (PMID 25109740, 2014). "PNFs are peripheral nerve tumors caused by bi-allelic loss of NF1 in the Schwann cell (SC) lineage." (PMID 40988822, 2025). "Targeting GPCR signaling has been suggested as a potential therapeutic option to treat NF1, so exploring the relevance of this pathway to peripheral nerve tumors is important." (PMID 35311647, 2022). "Contrast-enhanced MRI, PET, and functional and metabolic MRI techniques may help differentiate benign peripheral nerve tumors from MPNSTs in NF-1." (PMID 38013269, 2023).
Cowden syndrome (15 papers, 2011 to 2025). "Associations included NF1, polyposis coli, Cowden syndrome, familial hamartomatous polyposis syndrome, PTEN hamartoma tumor syndrome, familial adenomatous polyposis syndrome, and syndrome of watery diarrhea, hypokalemia, and achlorhydria." (PMID 37218882, 2023). "On the other side, MEN2B, NF1 and Cowden’s syndromes typically occur, associated with ganglioneuromatous polyposis and diffuse ganglioneuromatosis, rather than in association with isolated GNs." (PMID 33785023, 2021). "RET, PTEN, or NF1 mutations were detected to screen for MEN2B, Cowden syndrome, or NF1, respectively." (PMID 35783634, 2022). "The patient had no family or personal history of signs or symptoms related to other neural lesions or inherited syndromes such as NF-1, Cowden syndrome or MEN 2B." (PMID 21663626, 2011). "Colorectal neurofibroma is nearly pathognomonic of NF1, mucosal neuroma is highly associated with MEN 2B, and ganglioneuroma occurs frequently in association with Cowden syndrome, MEN 2B or NF1." (PMID 21663626, 2011). "However, ganglioneuromatous polyposis and diffuse ganglioneuromatosis often occur in association with NF1, MEN2b, juvenile polyposis, Cowden disease, and non-familial adenomatous polyposis." (PMID 31277169, 2019). "The patient has no clinical evidence of NF1, MEN2B, or Cowden syndrome, adding a non-syndromic adult case to the very limited literature on this entity." (PMID 41441535, 2025). "However, due to the unavailability of genetic testing in this patient, NF1, MEN2B, and Cowden syndrome cannot be ruled out." (PMID 35783634, 2022).
Spinal neurofibroma (15 papers, 2012 to 2025). A neurofibroma (benign peripheral nerve sheath tumor) localized in the spine. "Since the pNF developed at the sciatic nerve injury site, it bypasses the tedious and lengthy whole peripheral nervous system dissection normally required to isolate the ganglions where para-spinal neurofibroma develops in tissue-specific Nf1 knockout models." (PMID 38900740, 2024). "In our cohort, symptomatic spinal neurofibromas were significantly more frequent in the NF1-deleted patients (6/35 vs. 36/2,058; p value = 1.7 × 10−4 after correction for multiple testing)." (PMID 34199217, 2021). "NF1 deletion patients significantly more often presented with symptomatic spinal neurofibromas, cardiovascular and skeletal abnormalities, learning disabilities, dysmorphism, and malignancies when compared to a “classic NF1” cohort, in a cohort of 126 NF1 deletions patients." (PMID 38448973, 2024). "It was only realized later that the main manifestations of NF1 were either not recapitulate in mice (e.g. Lisch nodules, CALMs) or recapitulate only a rare subtype (e.g. para-spinal neurofibroma, diffuse cNF)." (PMID 38900740, 2024).
uveal melanoma (15 papers, 2013 to 2026). A melanoma derived from melanocytes of the uveal tract. "There were also two cases of uveal melanoma with NF1 copy-number loss among the 80 TCGA-UVM samples, and these cases had some other intriguing molecular features." (PMID 39804140, 2025). "We found that heterozygous 17q11.2 loss that includes the NF1 locus is a recurrent phenomenon in human intradermal and uveal melanomas described in the literature." (PMID 39804140, 2025). "Heterozygous 17q11.2 loss that includes the NF1 locus is an uncommon, but recurrent phenomenon in intradermal and uveal melanomas that we think should be considered a potentially significant finding." (PMID 39804140, 2025). "We found that heterozygous partial loss of chromosome 17, including the NF1 gene, recurs in uveal melanoma (2.5%) and blue nevus–type intradermal melanoma (14%)." (PMID 39804140, 2025). "We investigated the transcriptional changes that accompany Nf1 loss in the context of intradermal and uveal melanomas and found evidence for upregulation of cAMP signaling and downregulation of myogenesis gene expression, respectively." (PMID 39804140, 2025). "Genomic patterns of BAP1mut non-uveal melanomas differed substantially from those of uveal origin in terms of mutational load and driver oncogenes: NF1, BRAF, and NRAS mutations were frequent, often with numerous co-mutations." (PMID 38903495, 2024). "We found that Nf1 heterozygous loss accelerated the development of intradermal and uveal melanomas." (PMID 39804140, 2025). "High mutation numbers and frequent NF1 mutations may suggest that BAP1mut non-uveal melanomas tend to be hypermutated tumors." (PMID 38903495, 2024). "Therefore, we conclude that Nf1 loss promotes uveal melanoma driven by oncogenic GNAQ." (PMID 39804140, 2025). "In CMs, uveal melanoma-related hotspot mutations appear to often co-occur with the mutations affecting the CM driver genes such as BRAF, NRAS, KIT, NF1, and ATRX." (PMID 37761808, 2023). "Genes that were known to be mutated in cutaneous and uveal melanoma subtypes, including BRAF, NRAS, NF1, GNAQ and GNA11, were rarely mutated in our cohort of patients." (PMID 30847022, 2019). "There was an exceptionally clear signal from the Nf1-mutant uveal melanomas in GO analysis." (PMID 39804140, 2025). "Another study found that NF1 expression was downregulated in uveal melanoma." (PMID 39804140, 2025). "We identified BRAF mutations in 21/74 (28%) patients, NRAS mutations in 4/74 (5.4%) patients, NF1 mutations in 1/74 (1.4%) patients and GNAQ mutations in 1/74 (uveal melanoma) (1.4%) patients, as well as BRAF/NRAS (1/74; 1.4%) and GNAQ/NF1 (1/74; 1.4%) double mutations." (PMID 32785074, 2020). "This is supported by the finding of a constitutively active GNAQ mutation in an NF1+/− uveal melanoma, which otherwise might be redundant, if EDNRB/GNAQ signaling completely overlapped with NF1." (PMID 23555837, 2013). "No somatic point mutations in NF1 were found in uveal melanoma." (PMID 39804140, 2025). "No BRAF, NRAS or NF1 mutations were detected in uveal melanoma samples." (PMID 38903495, 2024). "Responses were seen in tumours harbouring BRAF fusions, GNA11, GNAQ, KRAS, NF1, and NRAS alterations, most frequently in low-grade serous ovarian cancer, central nervous system tumours, and uveal melanoma." (PMID 41664938, 2026). "GNAQ and GNA11 mutations were common in uveal melanomas, while MAP-Kinase mutations were frequent in non-uveal melanomas with NF1, BRAF V600 and NRAS Q61 mutations occurring in decreasing frequency, consistent with a strong UV association." (PMID 38903495, 2024).
autism spectrum disorder (14 papers, 2016 to 2026). A spectrum of developmental disorders that includes autism, and Asperger syndrome. "A higher incidence of autism spectrum disorder and cognitive problems in individuals with NF1 suggests that NF1 is linked with how Ras and other intracellular pathways are regulated." (PMID 37761518, 2023). "Additionally, our patient exhibited borderline intelligence and autism spectrum disorder, which have also been linked to NF1." (PMID 41001300, 2025). "Assessments revealed the complexity of NF1 phenotype and a variety of problems including learning difficulties, emotional problems and autism spectrum disorders." (PMID 32089936, 2019). "Here, we present unique gene expression profiles in iN cells from patients with neurofibromatosis type 1 (NF1), a single-gene multifaceted disorder with comparatively high co-occurrence of autism spectrum disorder (ASD)." (PMID 29066822, 2017). "Features of autism spectrum disorder occur in up to 30% of children with NF1." (PMID 36553485, 2022). "Interestingly, some studies showed a higher frequency of autism spectrum disorder in NF1 children, and this is a variable condition in NF1 that might be influenced by variants in other genes." (PMID 32858845, 2020). "In NF1, overactivation of RAS signaling can lead to excessive release of γ-aminobutyric acid, disrupting the balance between neuronal excitation and inhibition and potentially contributing to symptoms of autism spectrum disorder." (PMID 41001300, 2025). "While changes in gamma activity have been reported in autistic spectrum disorders, for which NF1 is a suitable model, we did not observe similar changes in the present study." (PMID 26881921, 2016).
breast tumors (14 papers, 2011 to 2025). "A recent study has shown that the loss of NF1 accelerates breast tumor formation in rats, and that low NF1 mRNA expression levels in human BC are associated with shorter patient survival times." (PMID 41155378, 2025). "NF-1 is also associated with other organ tumors, such as optic nerve glioma, gastrointestinal stromal tumors, and breast tumors." (PMID 37165249, 2023). "Somatic ARID1A, MLL3 and NF1 mutations were found in at least one component in three, six and four breast tumours, respectively, and the presence of these mutations was unrelated to the HER2 status." (PMID 32058674, 2020). "The authors suggest, p14ARF and CDKN2B‐AS1 might share a promoter, a fact supported by their discovery of a significant correlation in transcript levels of CDKN2B‐AS1 with those of p14ARF, p16INK4a, and CDKN2B in healthy tissue as well as breast tumor samples and NF1‐associated tumor samples." (PMID 35723634, 2022). "Consistent with activation of CDK4/6 by NF1 loss, clinical data indicate that CDK4/6 kinase activities negatively correlate with NF1 protein levels in breast tumors." (PMID 41226361, 2025). "Two years ago, she had undergone a mastectomy for a breast tumor, which was pathologically diagnosed as MPNST associated with NF-1." (PMID 37165249, 2023). "As our sequencing analysis of advanced HER2 + breast tumors identified recurrent mutations in multiple MAPK pathway members, we asked whether pathway activation through mutational mechanisms other than NF1 loss also promotes resistance to HER2i." (PMID 34795269, 2021). "Near complete loss of NF1 protein was readily detectable in the DCIS regions but not in the stroma, and this NF1-low expression state persists in locally invasive breast tumor cells." (PMID 37501682, 2023).
Costello syndrome (14 papers, 2011 to 2025). Costello syndrome (CS) is a rare multisystemic disorder characterized by failure to thrive, short stature, developmental delay or intellectual disability, joint laxity, soft skin, and distinctive facial features. "Activating mutations in Ras proteins themselves, as in Costello syndrome (caused by mutations in H-Ras), or inactivation of Ras-GAPs, as in NF1 patients (caused by mutations in the NF1 gene), result in aberrant signaling to Ras effectors." (PMID 24035394, 2013). "Changes in myelin have recently been correlated with changes in behavior, and NF1 and Costello syndrome patients are known to display frequent behavioral deficits; therefore, we tested whether behavior was altered in mice with elevated Ras-GTP in oligodendrocytes." (PMID 24035394, 2013).
medulloblastoma (14 papers, 2006 to 2026). A malignant, invasive embryonal neoplasm arising from the cerebellum. "Beyond NF1, data from medulloblastoma cohorts also demonstrate a markedly increased risk: the observed-to-expected ratio of secondary malignant neoplasms was 4.49 (95% CI: 3.53-5.62), with a particularly elevated ratio in the CNS (40.62; 95% CI: 25.46-61.51)." (PMID 41216086, 2025). "In this report, we present a case of medulloblastoma associated with NF1 that was successfully treated with chemotherapy alone." (PMID 41216086, 2025). "Further studies are needed to clarify the optimal management strategies for NF1-associated medulloblastoma." (PMID 41216086, 2025). "To date, only 10 cases of medulloblastoma in patients with NF1 have been reported, highlighting the extreme rarity of this association." (PMID 41216086, 2025). "Reports of medulloblastoma in patients with NF1 are extremely rare, with only 10 cases documented to date." (PMID 41216086, 2025). "In the absence of this data, we cautiously describe the lesion as a medulloblastoma occurring in a patient with NF1." (PMID 41216086, 2025). "Another limitation is the lack of comparative data on outcomes between NF1-associated and non-NF1 medulloblastoma patients treated with chemotherapy alone." (PMID 41216086, 2025). "Although NF1 is recognized as a cancer predisposition syndrome (CPS), meaning that patients have a higher lifetime risk of developing cancer due to underlying genetic factors, the development of medulloblastoma is extremely rare." (PMID 41216086, 2025). "A limitation of this report is that we cannot definitively prove that the medulloblastoma was directly caused by the NF1 germline mutation rather than representing an unrelated second primary tumor." (PMID 41216086, 2025). "This case of medulloblastoma in a pediatric patient with NF1 was managed without radiotherapy, resulting in more than 10 years of disease-free survival." (PMID 41216086, 2025).
optic nerve glioma (14 papers, 2014 to 2025). A glioma that affects the optic nerve. "NGS studies indicate that a child predisposed to optic nerve glioma due to NF1 and CDKN2A genetic variants inherits these conditions from their parents." (PMID 38540335, 2024). "Therefore, we can speculate that the patient is highly likely to have NF1-associated optic nerve glioma." (PMID 39669368, 2024). "Neurofibromin was identified as a regulator of mTOR signaling in the mid-2000s, based on observations of elevated activated S6 levels in NF1 patient-derived cell lines, NF1-mutant optic nerve glioma mouse models, and human pilocytic astrocytoma tumors." (PMID 41294711, 2025). "NF-1 is an autosomal dominant disorder characterized by multiple neurofibromas, multiple cutaneous café au lait spots, axillary freckling, optic nerve gliomas and skeletal abnormalities." (PMID 24739734, 2014). "Nf1 ± mice with conditional Nf1 inactivation in astroglial progenitors (GFAPCre; Nf1flox/− mice) develop low-grade optic nerve gliomas, similar to children affected with NF1 syndrome." (PMID 25008045, 2014). "Work by multiple laboratories has demonstrated that the Nf1+/- microenvironment accelerates or, in some cases, is even required for the genesis of multiple benign NF1-associated tumors, including PNF, optic nerve glioma, and papilloma formation, in response to carcinogenic insult." (PMID 38473354, 2024). "Moreover, NGS studies show that chromosomal alterations by NF1 and CDKN2A pathogenic gene variants contribute largely to the development of optic nerve glioma." (PMID 38540335, 2024). "Optic nerve glioma developed in approximately 15% of patients with NF1." (PMID 24711935, 2014). "Furthermore, while mutations in NF1 are observed sporadically in PA, these are almost exclusively associated with optic nerve glioma in patients with inherited germline NF1 mutation, rather than somatically acquired as observed in TK-RIG915." (PMID 33053751, 2020).
gastric cancer (13 papers, 2011 to 2022). A primary or metastatic malignant neoplasm involving the stomach. "In the gastric cancer study, the NF1 protein was associated with the T stage and TNM stage." (PMID 35559021, 2022). "A research reported that 58.1% (93/160) of the gastric cancer samples were NF1-positive as compared to 94.4% (151/160) of the matched normal tissue samples (p < 0.001), which was consistent with our results." (PMID 35559021, 2022). "CircRNA NF1 functions as a miRNA sponge, accelerating gastric cancer progression by absorbing miR-1610." (PMID 31506425, 2019). "miR-107 acts as an oncogene and regulates gastric cancer development and progression by targeting NF1, DICER1, FOXO1, and CDK825,27,28,41." (PMID 30258124, 2018). "The qRT-PCR results showed that 96.3% (154/160) normal and 72.5% (116/160) gastric cancer tissues demonstrated NF1 mRNA expression." (PMID 29137312, 2017). "Immunohistological staining showed that 94.4% normal tissue samples positively stained for NF1 protein compared to 58.1% in gastric cancer tissue samples." (PMID 29137312, 2017). "Our data showed that NF1 mRNA expression was significantly different between the gastric cancer and normal tissues (χ2=34.23, P<0.001)." (PMID 29137312, 2017). "Next, we performed real time quantitative PCR (qRT-PCR) to compare NF1 mRNA levels in gastric cancer and matched adjacent normal tissues." (PMID 29137312, 2017). "We have reported a rare gastric cancer in a patient with NF-1 with high serum levels of multiple serum tumor markers." (PMID 22018031, 2011). "Kaplan-Meier analysis revealed that negative or low NF1 were associated with poor overall survival (OS) in gastric cancer patients (P<0.001)." (PMID 29137312, 2017). "We report a rare case of advanced gastric cancer in a patient with NF-1." (PMID 22018031, 2011). "We investigated whether the Neurofibromatosis type-1(NF1) gene was of prognostic relevance to gastric cancer (GC) patients." (PMID 29137312, 2017). "The other component comprises several circuits involving miR-17, miR-195 and miR-497 together with NF1 (a hypoxia-activated gene), TFAP4 (another cancer gene with prognostic importance in gastric carcinoma), MYC and HNF1A, and common target genes, which can mainly be classified as cancer genes." (PMID 23987127, 2013).